NUTM2F (NUT family member 2F)
Synonyms: FAM22F; DKFZp434I1117; NUTMF
Tractability: No criterion of Open Targets' tractability assessment is met for any kind of drug.
Gene: Protein-coding gene on chromosome 9 (94,318,198 to 94,328,644, reverse strand). Ensembl gene ENSG00000130950.
Subcellular location (Human Protein Atlas): Nuclear bodies
Genetic constraint (gnomAD): Loss-of-function variants: 21 observed, 33.2 expected, observed/expected ratio (o/e) 0.63, 90% interval 0.45 to 0.91. The synonymous counts are far from expectation, so gnomAD's model fits this gene poorly and the ratio says little. Missense variants: 460 observed, 632.64 expected, observed/expected ratio (o/e) 0.73, 90% interval 0.67 to 0.79. Synonymous variants: 188 observed, 259.83 expected, observed/expected ratio (o/e) 0.72, 90% interval 0.64 to 0.82.
Homologues: Orthologues: rat Nutm2 (39% identical), mouse Nutm2 (37% identical). Paralogues in human: NUTM2G (97% identical), NUTM2B (84% identical), NUTM2D (84% identical), NUTM2A (84% identical), NUTM2E (84% identical), NUTM1 (47% identical).